MIR188 (microRNA 188)
Synonyms: hsa-mir-188; MIRN188; miR-188
Gene: MicroRNA gene on chromosome X (50,003,503 to 50,003,588, forward strand). Ensembl gene ENSG00000207768.
Gene Ontology:
Biological process: miRNA-mediated post-transcriptional gene silencing
Homologues: Orthologues: chimpanzee ptr-mir-188 (99% identical), macaque mml-mir-188 (98% identical), rabbit MIR188 (98% identical), rat Mir188 (88% identical), guinea pig MIR188 (78% identical), mouse Mir188 (78% identical). Paralogues in human: MIR660 (72% identical), MIR532 (67% identical).